CRP (C-reactive protein)
Diseases named in the same sentence as CRP in open-access papers (continued):
Sharing a sentence is not in itself a finding about the gene and the disease.
infection (continued). "In the discovery cohort, the combination of MRP8/14+CRP discriminated KD patients (n = 48) from patients with infection (n = 105), with area under the ROC curve (AUC) of 0.88." (PMID 32775314, 2020). "It was shown that there was respective statistical difference (P = 0.02 for ESR and P = 0.02 for CRP) pre‐ and post‐operation, which proved that the operation is effective in removing the lesion and controlling the infection." (PMID 32324329, 2020). "Although seeming to have average sensitivity and specificity, but as reported by Çetinkaya and coworkers, the increase in CRP levels is slow during the first 24–48 hours of infection, which negatively affects its sensitivity." (PMID 33061986, 2020). "CRP is protective against early-stage infection because of the ability of CRP-pneumococci complexes to activate the complement system." (PMID 33117400, 2020). "In the one UK study, clinicians were informed that a CRP level <20 mg/L suggested a serious infection was less likely compared to a value of >80 mg/L where serious infection was more likely." (PMID 32628707, 2020). "For the diagnosis of PJI, Di Cesare and colleagues found that serum IL-6 had a higher diagnostic accuracy compared with CRP and ESR in diagnosing infection following hip and knee replacement (97% and 83%, 69%, respectively)." (PMID 33008442, 2020). "sCD14 level not only increases in the first 24 h after the onset of infection, just before CRP and PCT, but also has a higher area under the curve (AUC, 0.97–0.99), being considered an efficient marker in diagnosing EOS." (PMID 33419284, 2020). "But the initial host response to the infection was already signalled by inverse changes in the CRP and PA slopes." (PMID 32100658, 2020). "Whereas several reactive proteins have well-defined specific clinical use (e.g., CRP and infection), the role of D-dimer remains to be better explored beyond a simple marker of thrombosis." (PMID 32864251, 2020). "Due to this rapid increase in serum levels of CRP, it is routinely measured as a clinical biomarker for infection or inflammation in the healthcare setting." (PMID 32117266, 2020). "Factors that can affect the diversity of high or low CRP levels include psychosocial stress, low education, antimalaria drugs, infections such as serositis, Body Mass Index (BMI), and ethnicity." (PMID 32695177, 2020). "We started from a principle that CRP is frequently measured on admission when infection is suspected." (PMID 33266250, 2020). "The correlation analysis related to infection revealed the relationship between CRP-proteins and a number of other parameters, such as the biomarkers of kidney function cystatin C as well as the total leukocyte particle concentration (LPC)." (PMID 32576278, 2020). "Levels of the CRP increase as a result of the inflammatory response to infection or tissue damage, and have been used to evaluate surgery technique, infection and pathology progress." (PMID 33059654, 2020). "C-reactive protein (CRP) is an acute-phase reactant that is synthesized by the liver in response to inflammation or infection." (PMID 32913691, 2020). "During infection, inflammation or tissue damage, CRP levels will rise acutely to elicit a sufficient immune response over a 24–72 h period." (PMID 32117266, 2020). "If levels of CRP are above 10 mg.dL− 1 after postoperative day four a postoperative infection can be suspected." (PMID 32825817, 2020). "The infection biomarkers of C-reactive protein (CRP) were elevated in five (50%), and procalcitonin was increased in two (28.6%)." (PMID 33194660, 2020). "Infection-related biomarkers, including procalcitonin and C-reactive protein, were also abnormal in almost all patients." (PMID 33304660, 2020). "Likely due to the cytokine storm, several infection-related biomarkers, including lactic acid, CRP, and IL-6, gradually worsened during hospitalization." (PMID 32851063, 2020).
infection (continued). "Among the APRs, C-reactive protein (CRP) is the most commonly used biomarker of infection in adults as well as fetuses and neonates." (PMID 33211747, 2020). "Engineered CRP (E-CRP) molecules have been reported recently; unlike wild-type CRP, passively administered E-CRP protected mice against infection even when E-CRP was injected into mice after twelve hours of administering pneumococci." (PMID 33552084, 2020). "CRP concentrations rise quickly and acutely in response to infection, whereas elevated AGP concentrations are indicative of longer-term exposure to inflammation." (PMID 32266402, 2020). "Nevertheless, ESR levels declined thereafter and only CRP remained to be significantly high at 12 weeks after infection." (PMID 32099022, 2020). "Similar to CRP, it is primarily affected by the patient’s inflammatory state, physical condition, recent new infections or other diseases unrelated to the original tumor and to a large extent by myelosuppression due to chemotherapy or radiotherapy." (PMID 33317597, 2020). "The predictive value of CRP varies among studies, however its potential use in detection of inflammation and/or infection is generally accepted." (PMID 32252639, 2020). "In terms of infection-related serum markers, studies show that C-reactive protein (CRP), IL-6, and erythrocyte sedimentation rate (ESR) are significantly increased in many patients." (PMID 33082858, 2020). "Due to the correlation between CRP and inflammation, CRP has attracted wide attention as a non-specific marker used for purpose of evaluation and monitoring of the infection and inflammation development as well as a prognostic marker for cardiovascular events." (PMID 32555600, 2020). "IL-6 is known to induce gene expression and release of CRP from the liver in response to inflammation or infection." (PMID 33198109, 2020). "As a traditional inflammatory marker, CRP is an acute-phase protein used for the diagnosis and follow-up of infection or tissue damage." (PMID 33026573, 2020). "Since complement activation by CRP-complexes is necessary for protection, endogenous murine CRP must have participated along with E-CRP-1 in protecting mice against infection." (PMID 33117400, 2020). "In 79 outpatients with a mix of ILI and other acute RTI, it was found that CRP > 5 mg/L had an odds ratio of 60 (CI 95% 2.7–1400; p = .010) for infection with influenza A or B compared to other viruses." (PMID 33174788, 2020). "Indications for a systemic administration of antibiotics include the diffuse spread of infection in the soft tissue and/or an infection-related general reaction of the body, such as shivering, fever, fatigue, neutrophilic leukocytosis and CRP elevation." (PMID 32373436, 2020). "We also noted in our study that, aside a positive RT-PCR, ESR and CRP were sensitive indicators of infection." (PMID 33883774, 2020). "Strong inflammatory responses as evidenced by elevation of PCT with high WBC and CRP levels were mainly observed among children with human adenovirus species B infection in this study." (PMID 33145348, 2020). "CRP, which is an acute-phase protein stimulated by infection, inflammatory diseases, tissue infarction, and neoplasia, is one of the essential molecules in host defense and regulation of cascaded inflammatory cytokines and monocyte-macrophage series." (PMID 32419794, 2020). "Our results suggested that CRP performed best in discriminating HAP with non-infection status as a single indicator." (PMID 32527243, 2020). "For another individual (W0022), the clinical chemistry result reveals elevated C-reactive protein (CRP) levels (79 mg/L) at visit two due to an infection." (PMID 32576278, 2020). "CRP has been commonly used as a marker for inflammation, infection, tissue damage, malignancy, and autoimmune diseases." (PMID 32695177, 2020). "Generally, CRP binds to different bacteria and increases their opsonization, earlier to the secretion of immunoglobulin specific to existent infection." (PMID 33240679, 2020).
infection (continued). "An elevation of CRP reflects an activation of immune responses which are often triggered by infections in critically ill patients leading to worse outcome." (PMID 32252639, 2020). "After the ROSC, SOFA scores; incidence of pre-TTM shock; peak CRP value and complication rates of seizures, infections were higher in patients with unfavorable outcomes; these patients had significantly lower pH and HCO3 after ROSC and higher PaCO2." (PMID 32927857, 2020). "The high WBC counts and CRP levels on PODs 3 and 6 show a prolonged postoperative infection in organ/space site, and suggest that intestinal edema and a prolonged decrease in intestinal absorption, which may be caused by infection in organ/space site, contribute to the pathology of HOS and OO." (PMID 32345295, 2020). "Inflammatory responses (S-04 E10 and S-18 E20) in SAA and CRP were measurable (1.3- and 2.2-fold increases in SAA from respective personal baselines), but were ∼100× smaller than those associated with major infections." (PMID 32253915, 2020). "The levels of the infection-related biomarkers CRP and IL-6 were significantly increased during hospitalization (P = 0.034 and P < 0.001, respectively)." (PMID 32851063, 2020). "Such depletion contributed significantly (P < 0.001) to decreasing the inhibitory infection capacity of the CRP treatments." (PMID 31953490, 2020). "CRP is an acute-phase reactant protein that exhibits elevated expression in response to injury, infection, and inflammation." (PMID 33324592, 2020). "Fourth, the CRP transition of this study includes a population for which treatment failure, including inadequate source control or other disease or infection, occurred during the clinical course." (PMID 32824569, 2020). "(ii) Immunologic sounding: Persistent local infection caused by P. gingivalis induces the upregulation of inflammatory cascades involving IL-1, IL-6, IL-8, TNF-α, CRP, and IFN." (PMID 33202751, 2020). "Currently, initial DNI with serum WBC and CRP which are commonly used markers is known to be useful for predicting inflammation and infection." (PMID 32075629, 2020). "We found Hb, CRP, N%, and PLT were indications when compared with ADV infection, among which CRP had the best performance." (PMID 32923416, 2020). "CRP exhibits elevated expression during inflammatory conditions such as rheumatoid arthritis, cardiovascular disease and infection." (PMID 32527243, 2020). "Biological findings were consistent with obvious infection as illustrated by a median C-reactive protein (CRP) at 77.8 (38.4–132.7) mg/l." (PMID 32472191, 2020). "C-reactive protein (CRP), another marker for diagnosing infections, is produced primarily by hepatocytes in response to infection." (PMID 32908505, 2020). "CRP, as an acute phase protein, increases significantly by destruction in organs, infection, and inflammation." (PMID 32104688, 2020). "Each combination of SOFA with risk factors (including prior hospitalization, intra-abdominal source of infection, C-reactive protein, and albumin) improved the predictive performance of the model to different degrees." (PMID 33267829, 2020). "CRP value of ≥ 10 mg/L is the most commonly cut-off used to identify infection in neonates and it is best measured within 24 to 48 h of onset of infection." (PMID 32750089, 2020). "After infection, albumin and glucose were significantly decreased, while blood phosphorus, lactate dehydrogenase, and CRP were significantly increased." (PMID 32722980, 2020). "Both findings seem reasonable as CRP is a surrogate parameter of inflammation and is widely used to detect severe infections." (PMID 32252639, 2020). "Previous research in Wuhan indicated that increased levels of CRP were indicative of a sustained inflammatory response subsequent to infection with SARS-CoV-2." (PMID 32589691, 2020). "During late-stage infection, pneumococci recruit factor H and become resistant to WT CRP-activated complement-mediated killing." (PMID 33117400, 2020).
infection (continued). "CRP is synthesized by hepatocytes in response to cytokines which are derived from leukocytes stimulated by infection, inflammation, or tissue damage." (PMID 32867787, 2020). "CRP rises quickly and acutely in response to infection, whereas AGP rises more gradually and is reflective of longer-term exposure to inflammation." (PMID 32266402, 2020). "The ratio of SAA over CRP (each in terms of fold-change from personal baseline average) shows large changes through the course of each infection." (PMID 32253915, 2020). "CRP is a plasma protein synthesized by the liver, and their numbers increase during infections and inflammation." (PMID 32695177, 2020). "On the other hand, C-reactive protein is an acute-phase reactant with prognostic significance in patients with infections, and its response to infection is determined by the invasive mechanisms as well as host predisposition." (PMID 33267829, 2020). "In our data, the values of risk of infection, such as ESR and CRP, were higher in all three groups during the perioperative period but had nonspecific markers." (PMID 34056129, 2020). "Thirty-four percent of the women had inflammation/infection (CRP > 5 mg/L and/or AGP > 1 g/L) with 14% of the women in the late convalescence stage." (PMID 32121000, 2020). "Due to the cytokine storm, infection-related biomarkers, including lactic acid, C-reactive protein, and interleukine-6, gradually worsened during hospitalization." (PMID 32851063, 2020). "In PUUV infection, on the other hand, IL-6 has predicted the outcome, but the predictive value of CRP is less clear." (PMID 31438470, 2019). "Preclinical data in the mouse and the homology with CRP, a molecule used to monitor inflammatory diseases and infection in clinical practice, prompted investigation of PTX3 as possible marker of human pathology." (PMID 31057548, 2019). "In healthy adults, CRP concentration varies between 0.068 and 8.2 mg/L; however, during an infection, CRP levels increase significantly." (PMID 31101112, 2019). "Serum C-reactive protein (CRP) is an acute phase protein induced mainly by IL-6 in response to inflammatory conditions, particularly infection." (PMID 31781117, 2019). "One possible explanation is that CRP is more easily affected by other factors (such as potential infection) than platelets." (PMID 31362703, 2019). "Ten studies examining the initial (i.e., upon infection) levels of CRP in patients with H1N1 were, therefore, selected for inclusion in the present review." (PMID 30288556, 2019). "In patients with inflammation and infection, CRP levels usually increase, and albumin levels are expected to decrease." (PMID 31803551, 2019). "C-reactive protein (CRP), resistin and P-selectin are serological inflammatory markers that rise during the acute stages of infection." (PMID 31856765, 2019). "We choose to define infection as positive swabs, elevated CRP, and diagnosed as clinically infected from the medical records as judged by the examiner." (PMID 30809423, 2019). "After the onset of infection or inflammation, CRP increases within 4–6 h and peaks at 36–72 h, while PCT rises within 2–4 h and reaches its maximum at 24–36 h." (PMID 31470804, 2019). "Both are acute-phase proteins whose concentrations reliably increase during infection and inflammation: CRP spikes in the early phase of infection while AGP rises more slowly and remains elevated during convalescence." (PMID 31469064, 2019). "Recently, the CRP/albumin ratio has been established as an independent prognostic marker in patients with infection, malignancy, and critical illness." (PMID 31781024, 2019). "In the serious infection group, all cases exhibited a high concentration of CRP, as well as PTX3 concentration." (PMID 31147578, 2019). "The values of procalcitonin, C-reactive protein, details of infection, and other clinical parameters were analyzed." (PMID 31777354, 2019).
infection (continued). "Our second model is an extension which accounts for extra variation in the leukocyte count due to a treatment adversity, infections, using C-reactive protein as a surrogate." (PMID 31792398, 2019). "AGP and CRP are both hepatocyte-secreted positive acute phase proteins, with the former playing an important role in human infection." (PMID 31309103, 2019). "CRP is commonly considered as a prognostic marker of severity related to cancer stage, severity of infection or both." (PMID 31438593, 2019). "Second, the infection must be controlled and keep a normal state in erythrocyte sedimentation rate and C-reactive protein level for more than 3 months before the bone graft." (PMID 31351451, 2019). "At the post-intervention blood sampling four subjects in the high-phytate bread group had CRP > 5 mg/L, and another four subjects gave positive answers regarding signs of infection or inflammation during the previous weeks." (PMID 29796932, 2019). "CRP levels are often low in healthy individuals but can increase quickly in response to inflammatory stimuli and other infection." (PMID 30893301, 2019). "CRP is an acute-phase protein produced following stimulation by various cytokines in response to infection, ischemia, trauma, and other inflammatory conditions." (PMID 31781024, 2019). "In summary, our results indicated that serum PCT and CRP are important indicators in diagnosing infection in children with malignant solid tumour." (PMID 30976022, 2019). "C-reactive protein (CRP) is an acute reactant protein that is rapidly released from the liver when induced by interleukin-6 in the presence of inflammation, cell injury, or infection." (PMID 31063484, 2019). "Eight studies also reported the prevalence of elevated CRP after excluding participants with suspected infection, defined as CRP >10 mg/L." (PMID 31258105, 2019). "IL-6 is considered the most important inducer of hepatocyte synthesis of acute-phase proteins in response to infection/inflammation stimuli, and CRP is produced mainly in the liver in response to IL-6." (PMID 31394828, 2019). "C-reactive protein (CRP) is an acute-phase reactant protein secreted by the liver in response to pro-inflammatory cytokines in the presence of inflammation, infection, trauma and underlying malignancy." (PMID 31281756, 2019). "Its levels increase more rapidly than CRP, between 2 and 6 hours and peak within 6–24 hours during infection." (PMID 31781117, 2019). "The model TCM-CRP extends TCM by incorporating C-reactive protein (CRP) measurements into the model as a surrogate for infections." (PMID 31792398, 2019). "Overall HRV decreases with age, is negatively associated with frailty status, and is inversely related to infection biomarkers such as C-reactive protein (CRP)." (PMID 30683068, 2019). "C-reactive protein (CRP) is a positive acute-phase reactant synthesized by the liver and used in the diagnosis of infections and/or evaluation of the effectivity of treatment." (PMID 31803551, 2019). "Inflammation parameters (ESR and CRP) are generally altered in the SLE during few conditions like infection or serositis." (PMID 31110478, 2019). "Both AGP and CRP are acute-phase proteins, but whereas CRP concentrations decline rapidly after infection, AGP falls off more slowly." (PMID 31093598, 2019). "When stratified by genotype distribution, mean CRP levels were significantly lower with infection with HCV genotype 1 and genotype 3 compared to HCV genotype 2." (PMID 30813467, 2019). "CRP is a positive acute-phase reactant significantly increasing during infection and/or inflammation, depending on the severity of the disease." (PMID 31803551, 2019). "A recently published study showed that CRP values >30 was uncommon in healthy term infants, supporting the decision of using 30 as cut of level for infection." (PMID 31709209, 2019).